HMGB1 (high mobility group box 1)
Diseases named in the same sentence as HMGB1 in open-access papers (continued):
Sharing a sentence is not in itself a finding about the gene and the disease.
prostate carcinoma (continued). "Patients who carried the HMGB1 rs1412125, rs1045411, and rs1360485 polymorphic variants were associated with a poorer prognosis of prostate cancer, including a higher D’Amico classification, higher pathologic Gleason grade group, higher pathologic T stage, and higher pathologic N stage." (PMID 33023053, 2020). "Similarly, overexpression of nuclear binding protein and proinflammatory mediator HMGB1 has been implicated in proliferation and metastasis of many cancer types, including prostate cancer." (PMID 24062781, 2013). "Recently, HMGB1 has been shown to be secreted from prostate cancer cells and its over-expression is associated with prostate cancer progression.Though HMGB1 can regulate gene expression, it acts primarily as a cytokine to promote angiogenesis and extravascular migration of inflammatory cells." (PMID 24212771, 2011). "However, the results of our study have demonstrated that the HMGB1 polymorphisms rs1412125, rs1045411, and rs1360485 were associated with prostate cancer disease progression and severity, suggesting more consistency of HMGB1 SNPs in the oncogenicity of various cancers." (PMID 33023053, 2020). "Meanwhile, androgen deprivation therapy (ADT) induces HMGB1 secretion and promotes prostate cancer metastasis in a paracrine form via HMGB1/RAGE." (PMID 40969278, 2025). "HMGB1, whose expression is significantly increased in prostate cancer specimens, has been reported to reactivate and interact with the AR signaling pathway to promote CRPC development in a non-androgen-dependent manner." (PMID 40969278, 2025). "In summary, HMGB1 plays a multifaceted role in prostate cancer progression, invasion and treatment resistance, becoming a potential therapeutic target and prognostic marker." (PMID 40969278, 2025). "In summary, HMGB1 exerts diverse functions in the advancement, metastatic potential, and therapeutic recalcitrance of prostate cancer, positioning it as a promising candidate for both targeted therapy and prognostic evaluation." (PMID 40969278, 2025). "HMGB1 significantly contributes to the advancement of prostate cancer while also is a huge hindrance during prostate cancer treatment." (PMID 40969278, 2025). "Future studies can further explore the specific mechanisms of HMGB1 in prostate cancer to develop new therapeutic strategies." (PMID 40969278, 2025). "HMGB1 plays a key role in the occurrence, development, and treatment resistance of malignant tumors of the urinary system (including prostate cancer, bladder cancer, and renal cell carcinoma)." (PMID 40969278, 2025). "In bladder and prostate cancers, treatment with chemotherapeutic agents such as gemcitabine or paclitaxel induces the release of HMGB1, which subsequently enhances autophagic activity via direct interaction with Beclin-1." (PMID 40969278, 2025). "In the prostate cancer cell line PC-3, silencing of the HMGB1 gene induced downregulation of key regulators of ribosome biogenesis and RNA processing such as OP1, RSS1, UBF1, KRR1, and LYAR." (PMID 37110415, 2023). "HMGB1 not only promotes TAM resistance in breast cancer but also participates in castration resistance in prostate cancer." (PMID 37375731, 2023). "HMGB1 expression is typically higher in prostate cancer cells undergoing metastasis and its expression exhibited a positive correlation with clinicopathological characteristics among prostate cancer patients concluding its prognostic relevance." (PMID 35829833, 2022). "In this way, exposing prostate cancer cells to gemcitabine significantly enhances the expression level of HMGB1." (PMID 35317831, 2022). "In this study, the IHC of 85 patients with prostate cancer tissues depicted a significant correlation between the HMGB1 and RAGE expression with clinicopathological characteristics and overall survival." (PMID 35829833, 2022). "HSP70 and HMGB1 is associated with the immunogenicity of 56°C and UVC-treated prostate cancer cells." (PMID 36278159, 2022).
prostate carcinoma (continued). "Other studies have shown that HMGB1 promotes the proliferation of prostate cancer by activating protein kinase B (PKB/Akt) pathway through BRG1." (PMID 35886594, 2022). "HMGB1 has been reported to interact with BRG1 to promote prostate cancer metastasis, and it is a potential therapeutic target to abrogate their interaction." (PMID 35152264, 2022). "Substantial expression of RAGE and HMGB1 is evident in the prostate cancer tissues when compared to the expression in untreated or hormone-refractory prostate cancer tissues." (PMID 35829833, 2022). "BRG1, the core subunit of SWI/SNF complex to regulate histone modification and gene transcription, can interact with HMGB1 to promote prostate cancer metastasis." (PMID 35152264, 2022). "The combined inhibition of IL6R and HMGB1 has been reported to be a new treatment for enzalutamide resistance in patients with advanced prostate cancer." (PMID 34858477, 2021). "THOC1, THOC2, THOC5 and THOC6, members of the THO subcomplex of TREX which participates in mRNA processing and transport of RNPs from nucleus to cytoplasm, are present in HMGB1 immunoprecipitates from ovary and prostate cancer cells." (PMID 34572914, 2021). "Consistent with our findings, HMGB1 was shown to promote prostate cancer development and metastasis by activating the Akt signalling pathway." (PMID 33391448, 2021). "In human prostate cancer cell lines, x-rays induce ATP and HMGB1 secretion at both 1×10 Gy and 10×1 Gy, but the latter elicits more HMGB1 release than the former in DU145 and PC3 cells." (PMID 34489957, 2021). "High-mobility group box 1 (HMGB1) was suggested as a promising therapeutic target for prostate cancer." (PMID 33023053, 2020). "Other types of malignancy in which the HMGB1/RAGE/NFκB axis appears to promote invasive potential include prostate cancer and HCC." (PMID 32664328, 2020). "The HMGB1 SNPs rs1412125, rs2249825, rs1045411, and rs1360485 in 579 prostate cancer patients and 579 cancer-free controls were analyzed with real-time polymerase chain reactions (real-time PCR)." (PMID 33023053, 2020). "In prostate cancer, it was found that targeting HMGB1 with short hairpin RNA (shRNA) in prostate cancer cells leads to an inhibition of prostate cancer cell survival." (PMID 33023053, 2020). "We show that NDV/FMW, an oncolytic NDV strain FMW, elicited the expression and release of several ICD markers, that is calreticulin (CRT), heat shock proteins (HSP70/90) and high‐mobility group box 1 (HMGB1), in prostate cancer cells." (PMID 32100392, 2020). "Further investigation of the possible involvement of HMGB1 in the pathogenesis of prostate cancer revealed that exposure of a prostate cancer cell line (PC3) to recombinant HMGB1 in vitro resulted in the epithelial-to-mesenchymal transition of these cells." (PMID 32664328, 2020). "Background and Aim: We have previously shown that high-mobility group box 1 (HMGB1) is an independent biomarker for shortened survival of prostate cancer (PCa) patients." (PMID 31410208, 2019). "Glycyrrhizin can attenuate the EMT of prostate cancer cells by suppressing HMGB1-involved signaling pathway." (PMID 31766574, 2019). "We have carried out the first HMGB1/HMGB2 interactome approach in prostate cancer (PCa) using both the PC-3 cell line and adenocarcinoma tissue." (PMID 31694235, 2019). "Another AGE receptor, RAGE, detects the danger signal/pro-inflammatory cytokine HMGB1, which plays an important role in prostate cancer metastasis development via NF-κB signaling." (PMID 30158439, 2018). "GA also presented anti-proliferative effects in leukemia and human ovarian cancer cell lines, and was shown to target prostate cancer cells via an anti-inflammatory pathway through downregulation of HMGB1, IL-6 and IL-8." (PMID 28415753, 2017).
prostate carcinoma (continued). "The potential importance of the HMGB1-RAGE interaction in promoting tumour progression is supported by a recent report showing that RAGE and HMGB1 are associated with the progression of prostate cancer and poor patient outcome." (PMID 27426915, 2016). "Another recent study demonstrated that HMGB1 released from dying cells induced secretory/cytoplasmic clusterin in prostate cancer cells." (PMID 26925422, 2016). "HMGB1 has been demonstrated to work together with prostate specific antigen (PSA) for predicting biochemical recurrence in prostate cancer or with squamous cell carcinoma antigen (SCCA) for early diagnosing recurrent cervical squamous cell carcinomas." (PMID 27391431, 2016). "In the LNCaP prostate cancer cell line, combined treatment with estrogen and cisplatin increases HMGB1 expression and apoptosis more than cisplatin alone and this effect is mediated by interaction between estrogen and ER-alpha." (PMID 26682011, 2016). "RAGE, receptor for advanced glycation end products, is another key inflammation transducer that can be activated by HMGB1 in prostate cancer cells." (PMID 24062781, 2013). "ADT induces HMGB1 secretion, which promotes prostate cancer progression." (PMID 40969278, 2025). "Future studies could further explore the specific mechanisms of HMGB1 in prostate cancer to develop new therapeutic strategies." (PMID 40969278, 2025). "When we administered glycyrrhizin or other HMGB1-neutralizing antibodies to desmoplasma-resistant prostate cancer cells that had developed resistance to paclitaxel, and then treated the cells again with paclitaxel, their sensitivity to paclitaxel was significantly restored." (PMID 40969278, 2025). "Additionally, a positive correlation has been revealed between metastasis to other sites and the activated RAGE/NF-κB signaling pathway, along with upregulated HMGB1 expression in prostate cancer cells." (PMID 38725632, 2024). "HMGB1 is a significant factor in the progression and invasion of prostate cancer." (PMID 37375731, 2023). "Researchers have found that alternol induces ICD in prostate cancer cell lines by increasing DAMPs levels (HMGB1, ATP release, and CRT translocation; pro-inflammatory cytokines such as IL-1 A, IL-1B, IL-8, and IL-6) and stimulating the immune response against tumors in prostate cancer cells." (PMID 37705051, 2023). "In addition, shedding of HMGB1 protein, a well-established marker for immunogenic cell death, was observed after exposure of prostate cancer cells to jin-3 reovirus." (PMID 34135475, 2022). "HMGB1 activates the Akt pathway through BRG1 to promote the proliferation of prostate cancer." (PMID 35886594, 2022). "Besides, HMGB1 can trigger chemoresistance feature of prostate cancer cells via activating downstream targets such as MYC/c-Myc signaling." (PMID 35317831, 2022). "HMGB1 overexpression promotes prostate cancer invasion via EMT induction." (PMID 35317831, 2022). "Therefore, HMGB1 induces autophagy to protect prostate cancer cells against gemcitabine-mediated cell death." (PMID 35317831, 2022). "A limitation of our study is that we lack data on HMGB1 mRNA or protein expression in prostate cancer patients, so more detailed analyses and evaluations could not be performed." (PMID 33023053, 2020). "Thus, in prostate cancer cells, glycyrrhicic acid affected epithelial-mesenchymal transition through regulation of high mobility group box 1 (HMGB1) proteins." (PMID 32878230, 2020). "Furthermore, our results showed a spatial and protein level correlation between HMGB1 and BRG1 in prostate carcinoma tissues (r2 =0.574, P<0.001) implying that HMGB1 modulates BRG1 function in prostate carcinoma progression." (PMID 31410208, 2019). "Our precious animal experience also revealed an rising HMGB1 level after cryoablation for prostate cancer, which indicated that danger signals may play a vital role in the cryo- immunological response." (PMID 31289616, 2019).
prostate carcinoma (continued). "HMGB1 expression is considered as a novel and independent predictor of decreased disease-free survival of patients with prostate cancer, and it may also be used as a novel and independent predictor of prognosis for OSCC patients." (PMID 28423715, 2017). "HMGB1 induced clusterin protected prostate cancer cells from docetaxel, an antitumor drug." (PMID 26925422, 2016). "It has also been observed that HMGB1 released from dying cells in prostate cancer induces the accumulation of tumour-infiltrating T cells and the expression of lymphotoxin-α1β2 on their surface, which in turn recruits macrophages to the tumour and supports angiogenesis." (PMID 27426915, 2016). "Consequently, silencing of HMGB1 or RAGE genes in prostate cancer cells resulted in decreased cellular viability." (PMID 26682011, 2016). "A previous study has demonstrated the significance of HMGB1 expression in prostate cancer." (PMID 24062781, 2013). "Knockdown of HMGB1 results in apoptotic activation in human prostate cancer cells." (PMID 24062781, 2013). "The HMGB1 SNPs may have the potential to predict prostate cancer disease progression." (PMID 33023053, 2020). "In contrast, verbascoside inhibits HMGB1 expression and downregulates TGF-β-related epithelial mesenchymal transition to reduce prostate cancer proliferation and invasion." (PMID 40969278, 2025). "In further studies, it was found that HMGB1 induces epithelial mesenchymal transition mainly by promoting overexpression of various matrix metalloproteinases with RAGE/NF-κB, which leads to prostate cancer metastasis." (PMID 40969278, 2025). "Verbascoside inhibits TGF-β and the EMT process through the HMGB1/RAGE axis, thereby reducing cell proliferation and invasiveness in prostate cancer via the PI3K/AKT/mTOR pathway." (PMID 38529373, 2024). "mRNA expression of HMGB1 and RAGE is upregulated in prostate cancer tissues, and increased RAGE expression induces the invasive ability of prostate cancer." (PMID 38529373, 2024). "Overexpression of high mobility group box 1 (HMGB1) resulted in poor prognosis in human bladder urothelial carcinoma and patients after radical prostatectomy in prostate cancer, while its overexpression in gastric adenocarcinomas yields favorable prognosis." (PMID 38730579, 2024). "HMGB1, combined with TNFR1, facilitates cancer progression and castration resistance by inducing NF-κB activation in prostate cancer." (PMID 37375731, 2023). "The administration with 18α-GA can prevent the invasion of DU-145 prostate cancer cells by downregulating the levels of NF-ĸB (p65), VEGF and MMP-9, as well as HMGB1 and IL-6." (PMID 36313350, 2022). "Some studies have pointed out that HMGB1 and BRG1 co-locate and interact with each other in prostate cancer cells, and HMGB1 can positively regulate the expression of BRG1." (PMID 35886594, 2022). "We also probed the blots with an antibody against the small GTPase RAB11, since this protein was identified in both HMGB1 and THOC5 interactomes in prostate cancer cells." (PMID 34572914, 2021). "Our results unequivocally demonstrated that Cabozantinib triggered ICD as defined by the simultaneous release of HMGB1 and ATP and the membrane exposure of CRT in human prostate cancer cells." (PMID 34745989, 2021). "However, it was unclear whether HMGB1 induced prostate carcinoma through PI3K/Akt pathway." (PMID 31410208, 2019). "Further, CP1 induced ICD in both mouse and human prostate cancer cells in vitro, as determined by increased HMGB1, ATP, calreticulin, and CXCL10, and in tumor tissue in vivo, as determined by HMGB1 secretion and increased cell surface calreticulin." (PMID 29686284, 2018). "A gankyrin/NONO/AR/HMGB1/IL-6/STAT3 loop in prostate cancer maintains HMGB1 expression and TAM-driven survival signaling." (PMID 41465435, 2025).
prostate carcinoma (continued). "gankyrin can cause prostate cancer progression by upregulating octamer-binding protein (NONO) expression, reactivating AR receptors, inducing HMGB1 transcription, and then promoting tumor-associated macrophage aggregation." (PMID 40969278, 2025). "In prostate cancer, RBBP7 interacts directly with HMGB1, which allows HMGB1 to participate in the RNA metabolic process and thus promotes cancer cell proliferation and differentiation, making the prognosis of patients with high HMGB1 expression worse." (PMID 38028543, 2023). "Taking advantage of our expertise using yeast tools, we carried out a Y2H approach to characterize proteins interacting with human HMGB1 and HMBG2 in prostate cancer and ovarian cancer cells; in both studies, we have found connections to ribosome biogenesis control." (PMID 37110415, 2023). "In addition, HMGB1 can induce EMT in some tumors, such as prostate cancer, hypopharyngeal carcinoma and non-small cell lung cancer (NSCLC), promoting cell migration and invasion." (PMID 32117622, 2020). "Furthermore, pharmacological repression of apoptosis, necroptosis, autophagy or endoplasmic reticulum (ER) stress exerted diverse effects on the HMGB1 and HSP70/90 evacuation in NDV/FMW‐infected prostate cancer cells." (PMID 32100392, 2020). "HMGB1 (2 μg/mL) induces EMT of colorectal and prostate cancer cells via the RAGE/NF-κB pathway." (PMID 31766574, 2019). "In contrast, HMGB1 expression was not affected in prostate cancer cells by miR-34a (data not shown)." (PMID 26313360, 2015). "Clinical studies also support that HMGB1 is overexpressed in PCa patients and may serve as a novel prognostic marker for BCR-free survival for prostate cancer patients after undergoing radical prostatectomy." (PMID 23766911, 2013). "In summary, YY1 is a recognized prostate cancer driver and different complexes in which YY1 takes part can induce activation or repression of gene expression, including also AR-YY1-mediated PSA transcription, which we found is also regulated by HMGB1 and HMGB2 silencing." (PMID 31694235, 2019).